IL1B (interleukin 1 beta)
Diseases named in the same sentence as IL1B in open-access papers (continued):
Sharing a sentence is not in itself a finding about the gene and the disease.
colitis (continued). "Models of experimental colitis have shown that macrophages promote crypt proliferation and that NLRP3 inflammasome production of IL-18 (not IL-1β) is required for epithelial protection." (PMID 24312491, 2013). "Multiplex analysis of 23 different cytokines and chemokines in serum collected at endpoint revealed significantly increased levels of IFN-γ, IL-1β, IL-17, MCP-1 and MIP-1β in mice with colitis, but not in mice treated with budesonide." (PMID 23226271, 2012). "Compared to WT colitis mice, lack of TNF-R1 resulted in significant up-regulation of IL-6, IL-1β, MCP-1, IL-17A levels in the colon tissues." (PMID 23285227, 2012). "In contrast to our results, other studies indicate an anti-inflammatory role for 17 HDHA, with negative correlations observed with IL-1β and other cytokines and adhesion molecules such as TNF-α, MIP-2, CXCL1/KC, VCAM-1, ICAM-1, and LFA-1 in an animal model of colitis." (PMID 41009650, 2025). "I3C did not alter TNF-α and IL-12 in male and female mice but increased the IL-1β and IL-6 in male mice and decreased IFN-γ in female and male mice, suggesting that I3C ameliorates colitis in females but not in males, indicating that I3C sex-specifically exhibits anti-colitis activity in mice." (PMID 40094833, 2025). "This could be the reason why the inhibition of MyD88 failed to mitigate the severity of colitis, as evaluated by DAI, HS, and several proinflammatory cytokines, including IL-1β, IFN-γ, and TNF-α." (PMID 38946731, 2024). "Treatment with VAS2870 ameliorated DSS-induced colitis with a reduction in DAI, MPO levels, macroscopic and histological scores, secretion of proinflammatory cytokines (TNF-α, IL-6, and IL-1β), and an increase in colon length, which were not affected by SS treatment." (PMID 37239114, 2023). "However, IL-1β, TNF-α, IgG, SOD, and MPO were not significantly affected by Gln, indicating that Gln is not so effective as Ala-Gln to suppress DSS-induced colitis." (PMID 34046146, 2021). "In this model the pro-inflammatory role of IL-1β seems to be non-redundant as treatment with a CASP1 or a NLRP3 inhibitor ameliorated established disease and prevented or delayed development of spontaneous colitis." (PMID 34344313, 2021). "Remarkably, data are claiming that the compound MCC950 can significantly suppress the release of proinflammatory cytokines IL-1β, IL-18, and IL1-α, contribute to inflammatory effects resulting from canonical and non-canonical NLRP3 inflammasome activation in colitis." (PMID 30873162, 2019). "Moreover, the observation that obestatin did not affect mucosal IL-1β concentration, and MPO activity in the colon of rats without induced colitis suggested that obestatin did not disturb the immune system when no signs of inflammation were present." (PMID 29865176, 2018). "In addition to assessment of tissue monocytes, we found that murine blood monocytes produced heightened IL-1β, but not TNF, during DSS colitis." (PMID 30542349, 2018). "However, we are surprising that TER did not protective effects on DSS-treated colitis in NLRP3−/− mice characterized by DAI scores, colon shortening, pathological changes, and IL-1β secretion." (PMID 28553294, 2017). "Rosmarinus officinalis L. oil, mainly constituted by 1,8-cineole along with α-pinene, camphor and p-cymene was only able to reduce the pro-inflammatory IL-6 production in the mouse colon in which colitis was induced by 2,4,6-trinitrobenzene sulphonic acid (TNBS), not suppressing IL-1β." (PMID 21160452, 2010). "It was observed that colitis did not interfere with the requirement of MPO activity and TNF-α levels, indicating that these inflammatory markers were not activated or deactivated and that other cytokines not investigated (IL-6 and IL-1β, e.g.)may be involved." (PMID 37577725, 2023).
colitis (continued). "However, it was not enough to prevent or reverse the course of acute colitis induced by DSS, as observed by macroscopic (colon length reduction), biochemical (increased IL-1β, TNF-α, and CXCL2/MIP-2), and histopathological analyzes of colonic tissues performed at the end of the experiment." (PMID 37685250, 2023). "The mucosal expression of mRNA for TNF-α, IL-1β, iNOS, COX-2, SOD-1, SOD-2, GPx mRNAs, and the hypoxia inducible factor (HIF)-1α protein expression were upregulated in colonic mucosa of treadmill exercising HFD mice with colitis compared with those without exercise." (PMID 31117199, 2019). "However, dextran sodium sulfate (DSS)-induced colitis could be mediated by the NLRP3 inflammasome activation-induced caspase-1 cleavage and IL-1β secretion, and mice lacking NLRP3 were significantly protected from colitis." (PMID 30696442, 2019). "Furthermore, the effect of protective construction disappeared and the expression of colonic MPO, IL-1β, IL-6, or TNF-α at the protein level was not counteracted by BD in PGF mice, indicating that the gut microbiota was essential for the effect of BD during colitis." (PMID 40745657, 2025). "However, we have shown previously that Il23a and Il1b mRNA is not induced directly by the LMP1/CD40-transgene, but rather a secondary effect of inflammation, as in B6DC-LMP1/CD40-mice on the Rag-ko background, these cytokines are not present and mice do not develop colitis." (PMID 30653608, 2019).
Sepsis (1,444 papers, 2005 to 2026). Sepsis is defined as life-threatening organ dysfunction caused by a dysregulated host response to infection. "IL‐10 helps prevent hyperactivation of the innate immune system by inhibiting the effects of cytokines such as TNF‐α, IL‐1β, and IL‐6, thereby reducing the risk of multiple organ failure, and mitigating complications related to sepsis." (PMID 41573125, 2026). "In M1 macrophages, HIF-1⍺ can lead to sustained production of the inflammatory factor IL-1β, resulting in further exacerbation of the inflammatory response, worsening sepsis-associated acute lung injury (SALI), and contributing to ARDS progression." (PMID 40887582, 2025). "In sepsis, high levels of proinflammatory cytokines (i.e., IL-6, IL-8, IL-18, and IL-1β) have been associated with higher mortality, a similar correlation in IE patients can be assumed." (PMID 41152385, 2025). "In LPS-induced sepsis mice, stefin B-deficient mice exhibited increased IL-1β secretion and TNF-α release was only significantly elevated at the 2-hour time point." (PMID 41017465, 2025). "The results identified BMI, sex, PCT, D-D, SOFA, APACHE II, IL-1β, and IL-17 as independent risk factors for poor prognosis in sepsis patients." (PMID 41305706, 2025). "Organ dysfunction in sepsis is often associated with elevated levels of cytokines such as IL-1β, IL-6, and TNF-α and activation of nuclear factor kappa B (NF-κB) pathways." (PMID 40896042, 2025). "Our findings indicate that cp‐OLA@MΦ NPs effectively neutralized key pro‐inflammatory cytokines such as TNF‐α, IL‐1β, and IL‐6, all of which are closely associated with the pathophysiology of sepsis." (PMID 39836501, 2025). "De novo serine synthesis deficiency also inhibits IL-1β production and alleviates lipopolysaccharide (LPS)–induced sepsis." (PMID 38758794, 2024). "By contrast, only GENT significantly suppressed the inflammasome-associated cytokine IL-1β compared to untreated sepsis, PTX or (GENT and PTX) in renal tissue and compared to PTX alone in blood plasma." (PMID 39963236, 2024). "Numerous studies have demonstrated that NLRP3-induced IL-1β release is the main cause of the brain dysfunction following sepsis." (PMID 38665289, 2024). "Specifically, we report here that CLP-sepsis caused a significant increase in IL-1β, IL-6, CCL3, CLL4, CXCL1, CXCL10 and GM-CSF, all of which contribute to sepsis-induced cytokine storm and, hence, to cardiac and organ dysfunction." (PMID 39559354, 2024). "Enhanced levels of IL-17 and of activation of its receptor also induce microglia activation and neuroinflammation, with increased TNFα and IL-1β brain levels, in a mice model of sepsis-associated encephalopathy." (PMID 38671534, 2024). "Early repetitive or chronic RIC administration has shown benefits in reducing levels of inflammatory cytokines (such as TNF-α, IL-1β, and IL-6) following lipopolysaccharide-induced sepsis and has been associated with a reduction in mortality in mice." (PMID 36445625, 2024). "Increased levels of IL-18 and its binding protein have been linked to the severity and progression of infectious diseases such as malaria while IL-1β and IL-6 are associated with sepsis and viral infections like COVID-19." (PMID 38251210, 2024). "Oxidative stress activates the inflammatory response, and the release of pro‐inflammatory factors TNF‐α and IL‐1β causes alterations in sepsis‐induced cognitive abilities." (PMID 39508266, 2024). "This aligns with previous findings suggesting that the course of inflammation during sepsis is closely linked to mature IL‐1β levels in the brain." (PMID 39370294, 2024). "Activated microglial cells in sepsis release IL-1β in microvesicles, which can potentially cause synaptic damage." (PMID 38384465, 2024). "Evidence supporting the efficacy of IL-1β inhibition in sepsis has predominantly been derived from NLRP3-deficient models." (PMID 39056754, 2024).
Sepsis (continued). "Previous studies have consistently demonstrated that Nlrp3 deficiency protects mice from lethal sepsis, which is associated with lower levels of IL-1β." (PMID 36798132, 2023). "The uncontrolled production of proinflammatory cytokines such as interleukin (IL)-1β activates systemic inflammation associated with sepsis and septic shock." (PMID 36720915, 2023). "Chorioamnionitis predisposes infants to PDA.Late-onset sepsis is associated with a higher rate of unsuccessful DA closure with treatment.Large PDA is associated with increased pro-inflammatory (IL-1β, IL-8) and anti-inflammatory (IL-1Ra, IL-10) cytokines." (PMID 36994431, 2023). "Genetic variants in IL-1β has been confirmed to be a risk factor for sepsis and MI, and contribute to the clinical course of sepsis." (PMID 37388447, 2023). "Second, it is difficult to understand a cause for diffuse IL-1β tissue production in sepsis as is thought to occur in CAPS patients." (PMID 37928695, 2023). "Immune cell activation via LPS from the cell wall of infecting bacteria during sepsis can cause the production of inflammatory cytokines such as IL-6, IL-1β, and TNF-α." (PMID 37761018, 2023). "IL-1β is known to be responsible for contributing to further damage during chronic disease and is implicated in many inflammatory conditions such as sepsis, inflammatory bowel disease, and rheumatoid arthritis." (PMID 37761018, 2023). "Conversely, men predominantly display Th1 responses and overproduce TNF-α, IL-1β, IL-2, IL-6, and IL-8, which in turn is often associated with poor outcomes, such as septicaemia and bacteremia." (PMID 37004108, 2023). "Our results showed that BPOZ-2 deficiency significantly increased serum IL-1β levels and accelerated sepsis-induced cell death." (PMID 36936774, 2023). "In particular, IL-1β plays a pivotal role in sustained neuroinflammation after sepsis and is closely implicated in memory processing and long-term potentiation, as well as neonatal sepsis-induced cognitive impairment." (PMID 35883093, 2022). "IL-1β is one of the “early” proinflammatory cytokines, also associated with increased mortality during sepsis." (PMID 35563475, 2022). "Overactive innate immunity, for example, the high production of IL-1β has been associated with higher sepsis associated mortality." (PMID 36026499, 2022). "Plasma concentrations of specific cytokines TNF-α, IL-1β, IL-6, and IL-8 are often elevated in patients with sepsis, and cytokine concentrations are associated with the severity and prognosis of sepsis." (PMID 36199375, 2022). "Activated microglia overexpress IL-1β, which can cause excitatory synaptic damage that leads to cognitive impairment in sepsis." (PMID 35642838, 2022). "During infection or sepsis, IL-1β can destroy the blood-brain barrier and increase the risk of patient mortality." (PMID 34860273, 2022). "The expression of the TXNIP-NLRP3 complex in monocyte-derived exosomes caused sepsis-related cardiovascular inflammation and myocardial dysfunction by promoting the activation of IL-1β and Interleukin-18 (IL-18) in macrophages." (PMID 36579343, 2022). "The up-regulation of TNF-α, IL-1β, and IL-6 has been confirmed to be inextricably associated with sepsis-elicited myocardial damage." (PMID 35599576, 2022). "Recently, we have shown that IL-1β is associated with muscle atrophy in a mouse model of polymicrobial sepsis." (PMID 35100595, 2022). "TNF-α and IL-1β following sepsis have also been considered as the critical factors causing cognitive impairment." (PMID 36552192, 2022). "Although the impact of GzmK absence in E. coli sepsis seems to be less pronounced than that of GzmA absence, GzmK deficient mice have shown significantly lower levels of IL-1β in serum compared with WT mice." (PMID 34815792, 2021). "AE and light are also effective in reducing biofilm formations, suppressing NO, IL-1β, IL-6, hemolytic activities, and inhibiting the expressions of toxins that cause sepsis." (PMID 34319262, 2021).
Sepsis (continued). "miR-128-3p mimics given before CLP operation effectively alleviated lung damage caused by sepsis, decreased activity of caspase-3 and cell apoptosis, and inhibited induction of IL-1β and IL-6." (PMID 34430706, 2021). "In accordance with the observation that IL-1β causes myocyte atrophy, Nlrp3-deficient mice are protected against sepsis-induced muscle atrophy." (PMID 34572540, 2021). "TNF-α provokes several inflammatory diseases, including cachexia, cytotoxicity, and sepsis, and IL-1β is believed to be associated in LPS-stimulated inflammatory processes." (PMID 35008520, 2021). "Proinflammatory cytokines, including IL-1β are key initiators of sepsis-associated life-threatening organ dysfunction." (PMID 34795266, 2021). "The effects of TRIM65 deficiency on LPS-induced sepsis were explored, and the outcomes showed that LPS increased IL-1β production in the sera of TRIM65-deficient mice." (PMID 34512673, 2021). "Here, we show that IL‐1β via its receptor and NF‐κB causes cardiomyocyte atrophy, which was accompanied by a reduced MyHC content, and that KO mice were protected from sepsis‐induced cardiac atrophy." (PMID 34472725, 2021). "We found that among sepsis-associated inflammatory cytokines (e.g., IL-1β, IFN-γ, TNF-α and G-CSF) and LPS, G-CSF and IFN-γ were found to significantly reduce DC development and functional differentiation." (PMID 34566996, 2021). "The NF-κB pathway has been reported to be a critical signaling pathway involved in the inflammatory response in sepsis, and cytokines, such as IL-1β and TNF-α, are associated with the activation of NF-κB." (PMID 34820388, 2021). "It is found that resveratrol exerts a protective effect on sepsis-associated encephalopathy by inhibiting the NLRP3/IL-1β axis of microglia." (PMID 34220338, 2021). "Beyond activating the endothelium and leukocytes, TNF-α, IL-1β, and IL-6 combine to induce the systemic acute phase response that is implicated in the development of sepsis." (PMID 32849612, 2020). "In sepsis and septic shock patients, upregulation of many cytokines, including IL-1β, IL-6, IL-8, IL-10, MCP-1, and G-CSF, was associated with increased mortality and positively correlated with patients’ SOFA scores." (PMID 32669536, 2020). "IL-6, TNF-α, IL-1β, and IL-12 are hallmark inflammatory mediators of sepsis that constitute the cytokine storm." (PMID 32153410, 2020). "IL-1β and IL-6 were also identified as prognostic indicators for sepsis-associated AKI due to their crucial function in local acute inflammation and acute renal damage." (PMID 32655407, 2020). "In this study, we demonstrated for the first time that complement activation during sepsis is associated with reduced C3aR expression and simultaneous increase of IL-1β expression." (PMID 32410859, 2020). "As an important mode of cell death in early sepsis, pyroptosis is likely to be a major cause of the immune storm because of its concomitant release of the proinflammatory factors IL-1β and IL-18." (PMID 32851082, 2020). "In this study, we found that the expression of NLRP3-associated proteins, including NLRP3, ASC, caspase-1, and IL-1β, was significantly upregulated at 12 and 24 h after sepsis." (PMID 32454788, 2020). "Excessive inflammatory response is associated with multiple organ failure and poor outcome in sepsis, and is characterized by enhanced expression of inflammatory factors including IL-1β, IL-6, and TNF-α." (PMID 33324396, 2020). "We found that lnc‐MALAT1/miR‐125a axis was positively associated with APACHE II score, SOFA score, Scr, CRP, TNF‐α, IL‐1β, IL‐6, and IL‐8, while negatively associated with albumin in sepsis patients." (PMID 32309886, 2020). "For example, stem cells were pre‐treated with IL‐1β (βMSC) and used in a sepsis model to observe their effect on liver, lung and kidney organ damage caused by sepsis." (PMID 32492261, 2020).